CLDN2 (claudin 2)
Diseases named in the same sentence as CLDN2 in open-access papers (continued):
Sharing a sentence is not in itself a finding about the gene and the disease.
colitis (continued). "Consistent with the results above, claudin-2 was reduced significantly in colitis model and overexpressed evidently in claudin-2 overexpression group." (PMID 34623552, 2021). "Claudin-2 overexpression was also found in miRNA-182-5p inhibitor group, strongly elucidating that inhibition of miRNA-182-5p exerts protective effects in colitis via targeting and up-regulating claudin-2 expression." (PMID 34623552, 2021). "On the other hand, both in human IBD and in DSS-challenged animals increased levels of claudin 2 were found and correlated with the severity of colitis." (PMID 33806347, 2021). "Claudin-2 was the binding target of miRNA-182-5p and was negatively regulated by miRNA-182-5p level in colitis model." (PMID 34623552, 2021). "This indicated that miRNA-182-5p functions in colitis via targeting claudin-2 and regulating claudin-2 expression." (PMID 34623552, 2021). "An upregulation of pore-forming claudin-2 and downregulation of sealing claudin-3 has been reported in ulcerative colitis, as well as in experimental colitis models, leading to altered TJ structure and barrier dysfunction." (PMID 34445403, 2021). "This notion is also supported by another study that used claudin-2 null mice to explore the effects of intraperitoneally injected TNFα and experimental colitis." (PMID 31726679, 2019). "In this study, our results demonstrate that SJZD ameliorates the severity of TNBS-induced colitis and downregulates the level of claudin-2 in colonic tissues." (PMID 28073341, 2017). "SJZD significantly ameliorated the severity of TNBS-induced colitis and downregulated the level of claudin-2 in colonic tissues." (PMID 28073341, 2017). "Statistical analysis showed that, in rat with DSS-induced colitis, claudin-2 expression in the DSS group was higher than that in the control group (P < 0.05) but was significantly lower than that in the QCWZD and mesalazine groups." (PMID 29234405, 2017). "Our present study also demonstrated that AMD3100 increased the expression of colonic claudin-1, claudin-3, claudon-5, claudin-7 and claudin-8, decreased of colonic claudin-2 expression in DSS-induced colitis." (PMID 22073304, 2011). "In colitis group, immunostaining of claudin-2 was increased in intensity, whereas the intensity of claudin-3 immunostaining was decreased." (PMID 22073304, 2011). "Treated with CXCR4 antagonist AMD3100 significantly promoted colonic claudin-1, claudin-3, claudin-5, claudin-7 and claudin-8 expressions, and also decreased colonic claudin-2 in colitis mice." (PMID 22073304, 2011). "Previous studies indicated that IL‐6 inhibition could ameliorate intestinal permeability in DSS‐induced colitis through the reduced expression of the intestinal tight junction protein, claudin‐2." (PMID 39815783, 2025). "Moreover, nobiletin treatment of the colitis group significantly reduced claudin-2 protein levels compared to the untreated colitis group, with localized expression in the lining glandular epithelium." (PMID 39334888, 2024). "On the other hand, claudin-2 was increased, which is expected to increase paracellular permeability, enhancing exposure of the lamina propria to microflora and creating electrolyte disturbance and the production of diarrhea in colitis." (PMID 39334888, 2024). "Although long believed to be a massive disturbance worsening the disease, it meanwhile has been shown that this water-flow induced by claudin-2 upregulation has more ameliorating effects, because in colitis models using claudin-2 knockout mice disease activity was higher." (PMID 39461590, 2024). "Loss of CLDN2 expression protects against CAC, despite promoting colitis." (PMID 37815870, 2023). "Colitis regulates CLDN2 expression in context-specific manner." (PMID 37815870, 2023). "To understand why CLDN2 loss promotes colitis but not CAC, we examined global transcriptomic changes in CAC-challenged Cldn2KO colons versus WT mouse colons." (PMID 37815870, 2023).
colitis (continued). "Irrespective, claudin-2 expression protects mice from DSS colitis." (PMID 37460613, 2023). "Interestingly, CLDN2 expression was downregulated in acute DSS-induced colitis colon samples although E-cadherin expression remained largely unaltered." (PMID 37815870, 2023). "RT-qPCR also confirmed the downregulation of Cldn2 expression in colitis." (PMID 37815870, 2023). "Interestingly, immunoblotting and IHC analyses showed a biphasic regulation of CLDN2 expression during colitis where CLDN2 expression was downregulated during DSS-induced acute colitis, but upregulated during recovery from colitis and in chronic colitis." (PMID 37815870, 2023). "We also found that mouse P2Y1R deficiency in mice significantly reduced goblet cell loss and intestinal permeability; increased the levels of tight junction proteins occludin, claudin-3, and ZO-1; and decreased claudin-2 in the colon tissues of mice with colitis." (PMID 37781034, 2023). "However, studies have demonstrated that claudin-2 can also increase intestinal epithelial cell paracellular permeability, leading to diarrhea, and is highly expressed in colitis patients’ colons." (PMID 36767519, 2023). "In light of above outcomes, we further examined whether expression of stem cell antigen-1 (SCA-1), associated positively with mucosal repair/regeneration, is upregulated in mice subjected to colitis/recovery and its potential correlation with CLDN2 expression." (PMID 37815870, 2023). "However, current study was undertaken to examine epithelial-intrinsic effects of claudin-2 expression under conditions of colitis/stress." (PMID 37460613, 2023). "pylori infection was used to test the hypothesis that exosomal CagA from H. pylori compromised the barrier integrity of the intestinal epithelium in colitis by facilitating Claudin-2 expression." (PMID 35331316, 2022). "Therefore, it is particularly crucial to determine the effect of L. gasseri JM1 on the mRNA expressions of intestinal tight junction proteins (Claudin-2, Claudin-3, Occludin and ZO-1) in mice with colitis." (PMID 36615796, 2022). "It was shown that mice overexpressing claudin-2 developed less severe colitis upon DSS treatment than wt mice, supporting the hypothesis of the “enteric tears” as a counter-regulatory process during development of the inflammation." (PMID 35563847, 2022). "In addition, it has been shown that DSS-induced colitis in mice was accompanied by an increase in the pore-forming protein Claudin-2." (PMID 36615796, 2022). "The effects of claudin-2 overexpression were investigated in colitis to determine whether inhibition of miRNA-182-5p functions via upregulation of claudin-2." (PMID 34623552, 2021). "Furthermore, a study reported that IL-6 monoclonal antibody treatment using DSS-induced colitis mouse models effectively suppressed the expression of claudin 2 and attenuated gut permeability." (PMID 34395495, 2021). "Claudin-2 overexpression resulted in improvement in the shortening of colonic length, the histopathological changes and colonic damage index, which was consistent with the effects of miRNA-182-5p inhibitor in colitis model." (PMID 34623552, 2021). "The claudin-2 level was declined evidently in colitis group." (PMID 34623552, 2021). "In addition, IL-13 can cause epithelial barrier disturbance by increasing epithelial apoptosis and upregulating the tight junction protein claudin-2 expression in the OXZ-induced colitis model." (PMID 31878303, 2019). "This indicates that IL-9 might disrupt intestinal permeability by enhancing the expression of claudin 2 in oxazolone-mediated colitis." (PMID 29881387, 2018). "In DSS-induced UC, QCWZD significantly alleviated colitis-associated inflammation, upregulated serum MSP expression and RON expression in the colon, reduced the pAkt levels, promoted colonic occluding and ZO-1 expression, and depressed claudin-2 expression." (PMID 29234405, 2017).
colitis (continued). "Moreover, in the present study, we found that treated with CXCR4 antagonist AMD3100 significantly promoted colonic claudin-1, claudin-3, claudin-5, claudin-7 and claudin-8 expressions, and also decreased colonic claudin-2 in colitis mice." (PMID 22073304, 2011). "Importantly, the weakened gut barrier in the colitis mice markedly recovered after transplantation of the SH‐modulated gut microbiota, as reflected by the upregulated expression of Occludin, Claudin‐2, Claudin‐3, and Claudin‐4 mRNAs and Occludin, Claudin‐3, and Claudin‐4 proteins." (PMID 38882491, 2024). "Therefore, based on the findings that claudin-2 KO mice develop severe colitis and epithelial injury when subjected to colitis, we postulated that autophagy targets claudin-2 to protect the IECs from stress-induced death and thus preserve the barrier integrity." (PMID 37460613, 2023). "The CLDN2/Survivin axis helps promotes MH and may inhibit progression of colitis to CAC." (PMID 37815870, 2023). "Hence, we examined if colitis-induced CLDN2 upregulation depends on EGFR activation." (PMID 37815870, 2023). "In addition, reduced TJ expression could accelerate mucosal inflammation (ulceration and colitis), as observed in claudin 2 and claudin 7 knockout mice, and claudin 2 overexpression investigations in mice." (PMID 32998222, 2020). "Moreover, the most important finding was that SJZD could upregulate the level of claudin 2 by immunochemistry in TNBS-induced colitis." (PMID 28073341, 2017). "Using a Salmonella-colitis mouse model and cultured colonic epithelial cells, we found that pathogenic Salmonella colonization significantly increases the levels of claudin-2 protein and mRNA in the intestine, but not that of claudin-3 or claudin-7 in the colon, in a time-dependent manner." (PMID 23505542, 2013). "However, the expression of colonic claudin-2 was significantly increased in colitis mice." (PMID 22073304, 2011). "p62/SQSTM1 targets claudin-2 for selective autophagy in stressed intestinal epithelium and protects mice from DSS-induced colitis." (PMID 39809743, 2025). "More relevant, while colonic claudin 2 expression increased permeability, it also increased colon length and protected against DSS colitis through lower colonocyte death on colitis, lower immune activation, and increases in regulatory T cells." (PMID 38531874, 2024). "This decrease was not significant (p = 0.065) in the proximal colon where no signs of colitis were detected, indicating that claudin 2 levels were associated with histological detection of colitis, and that they may be key to colitis resistance in Gbp5–/– mice." (PMID 38531874, 2024). "CLDN2 expression was examined in naive mice, mice subjected to DSS-induced colitis, colitis/recovery, or chronic-colitis." (PMID 37815870, 2023). "We demonstrate a potentially novel role of CLDN2 in promotion of mucosal healing in patients with IBD and thus regulation of vulnerability to colitis severity and CAC, which can be exploited for improved clinical management." (PMID 37815870, 2023). "Taken together, our data identifies claudin-2 as a selective substrate for P62/SQSTM1-assisted autophagy and its role in promoting survival against colitis-induced epithelial cell death to improve the gut barrier integrity." (PMID 37460613, 2023). "Coimmunofluorescence analysis was done using anti-CLDN2 and -SCA-1 antibodies using colons from the mice subjected to colitis/recovery." (PMID 37815870, 2023). "AhR activation by FICZ relieved colonic inflammation, reduced IL-6 and claudin-2 expression, and kept intestinal barrier function in a mouse model of DSS-induced colitis." (PMID 36678175, 2023). "We found a similar downregulation of claudin-2 expression in Caco-2 cells exposed to 2,4,6-Trinitrobenzenesulfonic acid (TNBS), also used to induce colitis in vivo." (PMID 37460613, 2023).
colitis (continued). "IL-13 secreted by ILC2 can induce epithelial cell SATA6 activation, which affects gut permeability and exacerbates experimental colitis, and STAT6 inhibition can reverse epithelial apoptosis and claudin-2 expression." (PMID 36032134, 2022). "It was demonstrated that claudin-2 is transcriptionally regulated by VDR in the healthy intestine; however, claudin-2 is hyper regulated through inflammatory signaling in colitis with reduced intestinal epithelial VDR." (PMID 35406694, 2022). "MiRNA-182-5p is capable of targeting claudin-2 which is one of the vital tight junction proteins and the effect and mechanism of miRNA-182-5p was explored here in the DSS-induced colitis model." (PMID 34623552, 2021). "In the present study, miRNA-182-5p was overexpressed in colitis model and inhibition of miRNA-182-5p alleviated experimental ulcerative colitis induced by DSS via targeting claudin-2 in vivo." (PMID 34623552, 2021). "Furthermore, in WT mice recovering from colitis, inhibiting EGFR signaling inhibited CLDN2 upregulation and MH." (PMID 37815870, 2023). "However, modeling of the pathological CLDN2 expression, as in IBD, protects mice from dextran sulfate sodium–induced (DSS-induced) or C. rodentium–induced colitis." (PMID 37815870, 2023). "Cldn2 and ZO1 are two TJ proteins involved in colitis disease pathology." (PMID 35263357, 2022). "Unlike ZO-1 and occludin, the expression of claudin 1 and claudin 2 was significantly upregulated in the majority of DSS-induced colitis mice when compared to the CTRL group without DSS treatment." (PMID 34395495, 2021). "The upregulation of claudin-2 has been observed in an IBD and colitis model." (PMID 32512895, 2020). "Nobiletin treatment of colitis did not significantly affect claudin-2 mRNA expression." (PMID 39334888, 2024). "We found similar CLDN2 upregulation in mice subjected to C. rodentium colitis (data not shown)." (PMID 37815870, 2023). "Indeed, claudin 2 was shown to be protective in chemically induced and pathogen-induced colitis but not in immune-mediated T-cell-transfer-induced colitis." (PMID 37239907, 2023). "However, mouse modeling of CLDN2 expression, as in IBD, unexpectedly protected from colitis." (PMID 37815870, 2023). "Genetic deletion of GBP5 in mice showed that mice without GBP5 were more resistant to developing colitis than wild-type littermates, with concomitant regulation of IRF4 phosphorylation and the tight junction marker claudin 2 in their colonic tissue." (PMID 38531874, 2024).
inflammatory bowel disease (39 papers, 2009 to 2025). A spectrum of small and large bowel inflammatory diseases of unknown etiology. "Most studies have shown that claudin-2 is highly expressed in crypt epithelial cells of mice with DSS-induced inflammatory bowel disease, causing an increasing of intestinal epithelial cell bypass permeability and damage to the mucosal barrier." (PMID 40362256, 2025). "It has reported that CLDN2 expression was elevated in active inflammatory bowel disease (IBD), adenomas, and IBD-associated dysplasia." (PMID 38425650, 2024). "According to previous studies, claudin-2 is normally tissue-specifically expressed in the small intestine and overexpressed in leaky epithelial tissues, such as the colonic tissues of inflammatory bowel disease." (PMID 35942211, 2022). "Cldn2 expression is upregulated by pro‐inflammatory cytokines and shows higher expression under inflammatory conditions such as inflammatory bowel disease." (PMID 33749879, 2021). "Claudin-2 as one of the tight junction proteins is downregulated in inflammatory bowel disease, which contributes to the further progress of IBD." (PMID 34623552, 2021). "The upregulation of CLDN2 expression has been coincidentally reported just in inflammatory bowel disease, and it is usually considered an indicator of inflammation." (PMID 31956411, 2020). "Some studies have demonstrated that inflammatory diseases, such as inflammatory bowel disease (IBD) and necrotizing enterocolitis (NEC), are associated with increased expression of claudin-2 and intestinal barrier defect." (PMID 28106723, 2017). "Of significance, Cldn2 expression is upregulated in the distal colon of patient with inflammatory bowel disease and in the urinary bladder of patient with IC." (PMID 28560313, 2017). "Both internalization of occludin and IL-13 induced claudin-2 upregulation have also been reported in human and experimental inflammatory bowel disease models." (PMID 27467505, 2016). "In previous studies, the paracellular channel claudin-2 has been reported to be induced by tumor necrosis factor α (TNFα), which explains e.g., the pathomechanism of inflammatory bowel diseases." (PMID 25009499, 2014). "It will be interesting to evaluate the possible role of GATA-4 in the increased expression of claudin-2 in different human epithelial pathologies, including inflammatory bowel disease and cancer." (PMID 23409073, 2013). "In particular, claudin-2 is known to be a leaky protein that contributes to inflammatory bowel disease and colon cancer." (PMID 23505542, 2013). "This is in keeping with our results that are the first to show AP-induced disruption of the claudin-1 distribution together with up-regulation of claudin-2, which is also the case in inflammatory bowel disease and destabilizes TJs." (PMID 19223985, 2009). "Increased intestinal permeability in patients with inflammatory bowel disease (IBD) is associated with the aberrant expression of the tight junction (TJ) protein CLDN2, and autophagy reduces epithelial permeability via CLDN2, which protects the epithelial barrier." (PMID 40001566, 2025). "Increased claudin 2 expression, particularly in the colon, is seen in studies of inflammatory bowel disease and ulcerative colitis; however, increased claudin 2 expression in those diseases is always accompanied by other markers of intestinal damage and inflammation." (PMID 36684095, 2023). "Furthermore, the expression of CLAUDIN-1 and CLAUDIN-2 appears elevated in inflammatory bowel diseases and is thought to contribute to tumor progression." (PMID 34638991, 2021). "After bioinformatics analysis (microRNA.org online tool), Claudin-2 is predicted to be the target gene of miRNA-182-5p and the effects of miRNA-182-5p on inflammatory bowel disease remains unknown." (PMID 34623552, 2021). "Increased claudin-2 and β-catenin expression were detected in active inflammatory bowel disease (IBD), adenomas, and IBD-associated dysplasia, but not in acute, self-limited colitis." (PMID 31726679, 2019).